RUNX2 (RUNX family transcription factor 2)
Diseases named in the same sentence as RUNX2 in open-access papers (continued):
Sharing a sentence is not in itself a finding about the gene and the disease.
periodontitis (33 papers, 2015 to 2026). An acute or chronic inflammatory process that affects the tissues that surround and support the teeth. "Immunohistochemical staining showed that both osteogenic-associated RUNX2 and Pan Kla were decreased in the periodontitis group compared to the control group." (PMID 38474198, 2024). "The analysis of gene expression in maxillae showed that periodontitis caused a significant decrease of Runx2 and OCN, as well as an increase of RANKL in Cre-negative control mice." (PMID 31921182, 2019). "Although RUNX2 has been implicated with the tooth development, its role in GFs and periodontitis remains underexplored." (PMID 27645561, 2016). "Research has revealed that the highly increased expression level of Runx2 in the gingival tissue of patients with periodontitis may be associated with the pathogenesis of periodontitis." (PMID 38069063, 2023). "Administration showed that moderate ER stress could inhibit alveolar bone loss in periodontitis by upregulating expression of RUNX2, COL1A1 and OCN." (PMID 36530443, 2022). "Studies using periodontitis rat models have shown that chronic intermittent hypoxia impairs periodontal bone formation by downregulating osteogenic markers such as RUNX2 and MDM21." (PMID 40995218, 2025). "In our in vivo study, a histological assay found that both osteogenesis-related protein RUNX2 expression and lactylation level were down-regulated in periodontitis." (PMID 38474198, 2024). "The difference in the area of positive areas for both RUNX2 and Pan Kla between the NC and periodontitis groups was statistically significant." (PMID 38474198, 2024). "The RUNX2 positive cells in the periodontal ligament and alveolar bone decreased in periodontitis group and was further reduced in SAH group." (PMID 38267969, 2024). "In OMV‐induced rat periodontitis, immunofluorescence was used to detect the expression of Runx2 and Osx." (PMID 39475060, 2024). "OPG and RUNX2 expression increased after GelMA action, while IL-10 decreased considerably compared to the periodontitis group; this expression was more pronounced in the RvD1 complexed with GelMA group." (PMID 39861667, 2024). "New bone significantly increased from day 14 after periodontitis induction, and the expression of Runx2 and OCN increased from day 7, suggesting that osteoblast differentiation factors are increased even before new bone formation." (PMID 37653550, 2023). "In ligature-induced periodontitis mice, the alveolar bone and osteoid areas, the osteoclast number, and the expression of Runx2, OCN, TRPC3, and TRPC6 was evaluated by H&E staining, TRAP staining, and immunohistochemistry, respectively." (PMID 37653550, 2023). "Another study reported that Runx2 expression in PDL cells was similar to that of the control group on day 14 after periodontitis induction." (PMID 37653550, 2023). "There is moderate evidence that P. intermedia is a pathogen associated with periodontitis, but we found that its pathogenic component, LPS, promoted osteogenesis and upregulated expression of COL1A1, OCN and RUNX2 in vitro." (PMID 36530443, 2022). "In this study, we designed the animal model of periodontitis and aimed to investigate the expression of miR-30a-5p and its effects on the osteogenesis and inflammation by targeting Runx2 in periodontitis." (PMID 34635105, 2021). "All suggested that miR-30a-5p involved in regulatory role of osteogenesis and inflammation targeting by Runx2 in periodontitis." (PMID 34635105, 2021). "That all suggested that miR-30a-5p-mediated-Runx2 provided a novel understanding of mechanism of periodontitis." (PMID 34635105, 2021). "Conversely, RUNX2 showed decreased connectivity in periodontitis samples." (PMID 41480557, 2026). "Runx2, a critical TF for osteoblast differentiation and bone formation, likely contributes to this cluster’s impaired regenerative processes of periodontal tissue destroyed by periodontitis." (PMID 40076622, 2025).
periodontitis (continued). "To explore the mechanistic role of PIEZO1 in TO-associated periodontitis progression, we performed immunohistochemistry (IHC) staining to analyze the expression of PIEZO1, interleukin (IL)-6, and runt-related transcription factor 2 (RUNX2) in PDL tissue." (PMID 41234768, 2025). "In a rat model with periodontitis, it was shown that a chronic intermittent hypoxic condition could impair periodontal bone formation by decreasing the osteogenic markers RUNX2 and MDM21." (PMID 37959214, 2023). "Our study provides novel mechanistic insights into the critical role of lncRNA SNHG5 as a miR-23b-3p sponge to regulate Runx2 expression in hPDLSCs and may serve as a potential therapeutics target for periodontitis." (PMID 37324192, 2023). "As the degree of periodontitis inflammation was cascaded by the obese status, the expression level of Runx2 in our study experienced a compensatory elevation for confronting or overcoming the negative effect of massive bone resorption and tissue reconstruction." (PMID 38069063, 2023). "After 14 days of periodontitis induction, the WT-ligature mice showed an increased expression of osteoclast markers Trap, Ctsk, Dcstamp, and Nfatc1 and decreased expression of osteoblast markers Runx2, Alp, Opn, and Osx, compared with the WT-sham group." (PMID 33869229, 2021). "However, whether miR-30a-5p targeting Runx2 influences the process of periodontitis remains unknown." (PMID 34635105, 2021). "Furthermore, we identified DLX5 regulating expression of the long variant of RUNX2 transcript, which was specifically active in GFs but not in their periodontitis-affected counterparts." (PMID 27645561, 2016). "Immunohistochemical staining demonstrated that the periodontitis group showed increased expression of the inflammatory marker (TNFα), along with decreased levels of AFF4 and osteogenic protein (RUNX2, COL1A1)." (PMID 37731335, 2024). "The differential gene heatmap and volcano plot showed that compared with the healthy group, osteogenesis-related genes, such as RUNX2, BMP2, and COL1, in the periodontitis group decreased significantly." (PMID 38474198, 2024). "In order to assess the impact of FK506/EPO on osteogenic differentiation in rats with periodontitis, we utilized immunohistochemistry methods to measure the levels of osteogenic markers, namely, Collagen I, OCN, OPN, and RUNX2." (PMID 38239915, 2023). "There is a mechanism of alveolar bone regeneration through the STRO-1, RUNX-2, OSX, OCN, and COL-I on the periodontitis model." (PMID 38107047, 2023). "There is a mechanism of alveolar bone regeneration through the STRO-1, RUNX-2, OSX, and the COL-I pathway in periodontitis models." (PMID 38107047, 2023). "Specific SNPs within RUNX2, CAMTA1 and VDR genes were associated with diversity metrics with no genome-wide associations detected for periodontitis severity or Mets components at p < 10−7." (PMID 38068972, 2023).
pancreatic cancer (32 papers, 2007 to 2025). "The expression of Runx2 in the cancer cells and the associated stromal fibroblasts in pancreatic cancer tissues prompted us to test the effects of coculture of IPSCs and Panc-1 cells on Runx2 expression as a naturally occurring process in vivo." (PMID 17876328, 2007).
pancreatic cancer (continued). "RUNX2, based on bioinformatics data, can act as a novel prognostic biomarker and a promising target in lung and pancreatic cancer." (PMID 41511334, 2025). "In pancreatic cancer, RUNX2 has been shown to regulate the transcriptional activity of the extracellular matrix proteins SPARC and MMP1, thereby influencing the tumor microenvironment." (PMID 40386045, 2025). "In pancreatic cancer, RUNX2 is also abnormally overexpressed, and its elevated expression is associated with the malignant behavior of the tumor, demonstrating significant diagnostic capability." (PMID 38430423, 2024). "RUNX2 appears to be an inferior prognostic biomarker in cohorts of patients with glioma, colorectal cancer, stomach cancer, pancreatic cancer, renal cancer, urothelial cancer, lung cancer, and cervical cancer." (PMID 37108164, 2023). "For instance, miR-205 was down-regulated in pancreatic cancer samples, and elevated miR-205 levels inhibited pancreatic cancer cell proliferation via RUNX2." (PMID 33402116, 2021). "RUNX2 is highly expressed in pancreatic cancer, liver cancer, and other malignant tumor tissues; hence, the knockdown of RUNX2 expression can inhibit its malignant biological behavior in cell experiments." (PMID 33071648, 2020). "Subsequently, we summarize the current understanding of oncogenic potential of RUNX2 and possible involvement of RUNX2 and various miRNAs in pancreatic cancer." (PMID 29558908, 2018). "From the clinical point of view, the elevated expression level of RUNX2 has been shown to correlate to poor prognosis of patients with pancreatic cancer or with thyroid cancer." (PMID 29558908, 2018). "Together, these observations suggest that RUNX2-targeting miRNAs effectively suppress the progression and/or metastasis of various types of aggressive tumors including pancreatic cancer." (PMID 29558908, 2018). "Consistent with our present observations, we have recently demonstrated that TAp63 is up-regulated in RUNX2-depleted pancreatic cancer AsPC-1 cells, and also found the putative RUNX2-binding consensus sites within the 5′-upstream region of TAp63 gene." (PMID 27713122, 2016). "Since Runx2 expression is regulated by factors released from both pancreatic cancer cells and pancreatic stellate cells, we sought to analyse the effects of different growth factors and cytokines on Runx2 expression in these cells." (PMID 17876328, 2007).
pancreatic cancer (continued). "Irrespectively, our results show that cancer and/or stromal cells-derived factors like TGF-β1 and BMP2 have the capacity to modulate Runx2 expression in pancreatic cancer and stellate cells in an autocrine/paracrine fashion." (PMID 17876328, 2007). "Pancreatic cancer cells were positive for Runx2 in 10 out of 20 cases and demonstrated both cytoplasmic and nuclear staining." (PMID 17876328, 2007). "The transcriptional activity of Runx2 target genes was studied in IPSCs and Panc-1 pancreatic cancer cells." (PMID 17876328, 2007). "This is also indirectly supported by the observation that FGF2 and Shh, which are known to increase pancreatic cancer cell growth and invasion, led to reduction of Runx2 mRNA expression in Panc-1 pancreatic cancer cells." (PMID 17876328, 2007). "Elevated RUNX2 expression has also been reported as a prognostic marker of poor clinical outcome and a promising molecular target for the treatment of the patients with pancreatic cancer." (PMID 37256183, 2023). "Taken together, the results show that miR-221-3p may act as an underlying tumour marker for prognosis prediction in pancreatic cancer and may work by acting on KIT, CDKN1B, RUNX2, and BCL2L11 expression." (PMID 32943991, 2020). "These miRNAs such as miR-203, miR-204, miR-205 and miR-217 negatively regulate RUNX2 expression, raising a possibility that miRNA-induced down-regulation of RUNX2 contributes to the suppression of malignant properties of pancreatic cancer cells such as drug resistance." (PMID 29558908, 2018). "Moreover, a growing body of evidence implies that a variety of miRNAs suppress malignant phenotypes of pancreatic cancer cells including drug resistance through the down-regulation of RUNX2." (PMID 29558908, 2018). "GO enrichment of each ColX module revealed multiple genes implicated in ossification, such as RUNX2 and TGFB3, both of which have been shown to play a role in OA, influence developmental pathways such as Wnt signaling, and contribute to EMT in breast and pancreatic cancer." (PMID 39939916, 2025). "Furthermore, miRNAs targeting RUNX2 suppress malignant phenotypes of pancreatic cancer cells, suggesting that the delivery of chemically stable synthetic miRNAs to pancreatic cancer tissues is an attractive strategy to treat advanced pancreatic cancer patients." (PMID 29558908, 2018). "Transcription levels of RUNX1, RUNX2, and RUNX3 were all increased in most types of cancers, including breast, esophageal, head and neck, and pancreatic cancer." (PMID 34485309, 2021). "Runx2 – in turn – suppresses the transcription of extracellular matrix modulators such as SPARC and MMP1, and thereby influences the pancreatic cancer microenvironment." (PMID 17876328, 2007). "The result of the PPI network projected four genes (KIT, CDKN1B, RUNX2, and BCL2L11) as hub genes in pancreatic cancer, which may be possible targets of miR-221-3p." (PMID 32943991, 2020).